IRAK1 (interleukin 1 receptor associated kinase 1)
Diseases named in the same sentence as IRAK1 in open-access papers (continued):
Sharing a sentence is not in itself a finding about the gene and the disease.
tumor (continued). "In vivo experiments also provide a theoretical basis for more effective tumor control in IRAK1 depletion combined with the IR group." (PMID 37031183, 2023). "TRAF6 was expressed at high levels in the cellular tumor zone and pseudopalisading cells around necrosis while in the microvascular proliferation zone and cellular tumor zone, IRAK1 was expressed at high levels." (PMID 37391426, 2023). "Relevant to this point, our data show for the first time that PTX3 exerts its pro-tumor activity in TNBC by activating TLR4/IRAK1/NF-kB signaling in tumor cells." (PMID 37749607, 2023). "The paradoxical effects of IRAK1 on tumor response would, at first glance, pose therapeutic conundrums." (PMID 37031183, 2023). "IRAK1 is overexpressed in many tumors and has been demonstrated to either directly or indirectly contribute to tumor progression and aggressiveness." (PMID 37370720, 2023). "In other words, IRAK1 inhibition would be expected to sensitize tumors to IR but at the expense of thwarting IR-induced anti-tumor immunity." (PMID 37031183, 2023). "In liver cancer, overexpression of IRAK1 was found to be critical for the maintenance of aggressive tumor-initiating/stem cells." (PMID 37370720, 2023). "For instance, IRAK1 is highly expressed in multiple cancer cells and is a critical driver of intrinsic tumor resistance to radiotherapy (RT) and chemotherapy." (PMID 37370720, 2023). "The downregulation of IRAK1 expression in HCC using IRAK1 siRNA was also observed to inhibit tumor growth and enhance sensitivity to cisplatin-induced apoptosis." (PMID 37370720, 2023). "Further analysis of the relationship between IRAK1 and tumor immune-infiltrating cells showed that IRAK1 was positively correlated with M2 macrophage cells and negatively correlated with CD8+T cells in multiple tumors." (PMID 35669566, 2022). "We monitored the volume of xenograft tumors and found that the silencing of IRAK1 significantly slowed tumor growth in vivo (tumor volume in NC vs sh-IRAK1 group: 941.9 ± 104.4 vs 377.0 ± 52.5 mm3, Figures 10iand 10j)." (PMID 35211171, 2022). "Then, we investigated IRAK1 protein expressions from the HPA database, which provided the IHC results of IRAK1 expression in tumor and normal tissues." (PMID 35669566, 2022). "In tumor samples from ccRCC patients, we observed a significant increase in the level of the c-Met receptor, IRAK1 and a decrease in MCPIP1 with respect to normal kidney tissue." (PMID 36138026, 2022). "IRAK1 expression correlated positively with pathology stage and tumor grade (for the latter there was only a slight trend)." (PMID 36421353, 2022). "There were 19 cancer types with significant differences in IRAK1 expression between tumor and adjacent normal tissues (p < 0.01)." (PMID 36421353, 2022). "High expression of IRAK1 was observed in pan-cancer patients with subtypes C1, C2, and C6, implying a tumor-supportive role of IRAK1." (PMID 35211171, 2022). "We found that in each case analyzed, the level of IRAK1 in the tumor tissue increased drastically compared to that in the normal tissue." (PMID 36138026, 2022). "There are reported synthetic IRAK1 inhibitors designed for therapeutic purposes against tumor or inflammatory diseases." (PMID 36421353, 2022). "The reduction in miRNA-192-5p expression promotes IRAK1 expression in endometrial cancer cells and activates NF-κβ signaling, inhibiting apoptosis and promoting tumor development." (PMID 35832790, 2022). "We analyzed IRAK1 mRNA expression in tumor and normal tissue samples across 33 pan cancers from the TCGA database." (PMID 35669566, 2022). "In our study, we initially used GEPIA2, TIMER, and HPA databases to determine the mRNA, protein expression level of IRAK1 in cancers compared normal tissues, and found that its expression was significantly higher in 20 tumours." (PMID 35669566, 2022).
tumor (continued). "After defining the associations with ICPs, we examined the relationship between IRAK1 and tumor-infiltrating immune cells in cancers using the CIBERSORT algorithm." (PMID 35669566, 2022). "There are reports on synthetic IRAK1 inhibitors designed for therapeutic purposes against tumor or inflammatory diseases, such as JH-I-25, oxfendazole (repurposed), and others." (PMID 36421353, 2022). "We now demonstrate that FGFR1-driven methylation mediates suppression of miR-146b-5p, which leads to tumor development as a result of increased IRAK1 expression." (PMID 34906138, 2021). "Most previous investigations implicate IRAK1 in tumor cell survival through its anti-apoptosis effect, as pharmacological inhibition or RNAi knockdown of IRAK1 results in apoptosis." (PMID 34906138, 2021). "These cells were then co-cultured with CD8+ T cells from tumor-free mice engrafted with the IRAK1 KO cells in different ratios and proliferation was determined using flow cytometry." (PMID 34906138, 2021). "In particular, miR-146b targets the IL-1 receptor-associated kinase 1 (IRAK1), in which its inhibition is correlated with increased PTC cell proliferation, tumor invasiveness, and aggressiveness, probably due to the deregulation of the E-cadherin-mediated EMT." (PMID 35186709, 2021). "When the same experiments were performed using CD4+ cells from tumor-free mice engrafted with the IRAK1 KO cells, we saw the same MDSC-mediated suppression of proliferation." (PMID 34906138, 2021). "We now demonstrated in the SCLL model presented here, however, IFN-γ secretion by the leukemic cells promotes tumor development by inducing MDSCs as part of an IRAK1-dependent mechanism." (PMID 34906138, 2021). "The CD8+ T-cell population was recovered from tumor-free mice engrafted with the IRAK1 KO #7 cells and naive BALB/C mice and then co-cultured in vitro with BBC2 KO#7 cells at different ratios." (PMID 34906138, 2021). "The tumor clearance activity of CD8+ T-cells from IRAK1 KO cell-engrafted mice was further examined using tumor cell killing assays." (PMID 34906138, 2021). "It associates with interleukin 1 receptor-associated kinase 1 (IRAK1) and IRAK4 to promote tumor survival." (PMID 33322508, 2020). "(iii) IR-induced activation of IRAK1, as assessed by T209 phosphorylation, systematically correlated with tumor cell line sensitivity to RT+IRAK1i." (PMID 31799178, 2019). "A comparison of expression of IRAK1 in metastatic clinical tumor samples showed that the expression and activity of IRAK1 increased when the tumor was metastatic, thus became more sensitive to IRAK1 inhibition." (PMID 32489949, 2019). "Complementing our microarray analyses with that of exome sequence datasets from radioresistant tumors across tumor spectra will further clarify the extent to which IR-induced IRAK1 signaling drives R-RT in human cancer." (PMID 31799178, 2019). "IRAK1 acting both as a driver of intrinsic tumor R-RT and as an effector of RT-induced antitumor immunity would, at first glance, pose obvious therapeutic conundrums." (PMID 31799178, 2019). "IRAK1 inhibitors would be expected to sensitize the irradiated tumor to RT but simultaneously thwart RT-induced antitumor immunity as initiated by stromal dendritic cells." (PMID 31799178, 2019). "Based on this study, the inhibition of IRAK1 is proposed as a new potential therapeutic strategy in this tumor." (PMID 30942869, 2019). "Conversely, TLR agonist-based immunotherapy would be expected to intensify RT-induced antitumor immunity but at the expense of fueling IRAK1-mediated cell survival in the irradiated tumor." (PMID 31799178, 2019). "EC cells stably transducted with IRAK1 siRNA produced significantly lower tumor growth rates in nude mice compared with control cells." (PMID 30279971, 2018).
tumor (continued). "The study found that IRAK1 levels are elevated in EC, with higher expression significantly correlating with poorer survival, and also correlating with higher tumor stage, lymph node metastasis, and myometrial invasion." (PMID 30279971, 2018). "IRAK1 tumor levels correlate with survival, stage, metastasis, invasion; knockdown in cells antiproliferative via cell cycle arrest, apoptosis; IRAK1 siRNA transducted cells less tumorigenic in mice." (PMID 30279971, 2018). "Rates of positive IRAK1 expression significantly correlated with large tumor size (P = 0.047) and the presence of metastasis (P = 0.041)." (PMID 30279971, 2018). "Significantly higher cytoplasmic, lower nuclear IRAK1 expression in tumor cells than normal epithelium; overexpressed early in sequential preneoplastic evolution." (PMID 30279971, 2018). "We also confirmed that miR-146b promotes aggressive tumor characteristics in PTC by suppressing IRAK1 expression and that restoration of IRAK1 expression reversed this outcome." (PMID 28294980, 2017). "The importance of targeting IRAK1 in HCC was emphasized by demonstrating that treatment with IRAK1 siRNAs suppressed HCC tumor growth in xenograft model." (PMID 27619757, 2016). "To further study the promoting-tumor effects of IRAK1 in vivo, we employed SMMU-7721 HCC exnograft models." (PMID 27619757, 2016). "At the same time, a small molecule possessing anti-inflammatory and anti-tumor effects was found to inhibit IRAK1." (PMID 27504095, 2016). "For example, miR-146a down-regulates the expression of TRAF6 and IRAK1 to suppress the activity of the NF-κB signaling pathway and has a key role in suppressing tumorigenesis and tumor progression by inhibiting tumor cell migration and invasion." (PMID 27683641, 2016). "The average tumor volumes and weights in the IRAK1/4 inhibitor-treated groups were also smaller than those in the DMSO groups (p < 0.05)." (PMID 27619757, 2016). "We detected significant increased IRAK1 expression in metastatic clinical tumour samples compared with matched primary tumours." (PMID 26503059, 2015). "Of further note, the expression levels of IRAK1 were in particular higher among tumours of the basal subtype when compared with other subtypes (P<0.0001, Tukey's multiple comparisons test)." (PMID 26503059, 2015). "We found that IRAK1 is expressed in much higher levels in poorly differentiated high grade (grade 3) tumours compared with relatively well-differentiated grade 1–2 tumours, as revealed by both Oncomine analysis and IHC verification." (PMID 26503059, 2015). "IHC analysis of the affected lungs indicated increased expression of IL-6 in tumours expressing ectopic IRAK1." (PMID 26503059, 2015). "Our data identified IRAK1 as a component of the DEK-dependent transcriptome whose expression in HNSCC contributes to tumor cell survival." (PMID 26527316, 2015). "IHC analysis of the harvested tumours indicated the corresponding changes of IRAK1 and IL-6 expressions in IRAK1-depleted tumours and in ectopic IRAK1-rescued tumours compared with control tumours, although cell proliferation marker Ki67 remained unchanged." (PMID 26503059, 2015). "IRAK1-inh treatment also reduced lung metastasis burden and markedly reduced the p-IRAK1 level in mammary pad xenograft tumour tissues." (PMID 26503059, 2015). "IRAK-1 was the next most frequently expressed with appreciable levels (medium to high) in all tumor samples analyzed." (PMID 25452754, 2014). "miR-146a has been identified as a tumor suppressor through down-regulation of the NFkB activators IRAK1 and TRAF6." (PMID 23554878, 2013). "Notably, CHMP4B and IRAK1 showed distinct expression patterns in different immune cell populations, indicating their potential roles in shaping the tumor immune microenvironment." (PMID 41760846, 2026). "Furthermore, immune infiltration analysis suggested roles for CHMP4B and IRAK1 in modulating the tumor immune microenvironment." (PMID 41760846, 2026).
tumor (continued). "As further proof of principle, we next evaluated the effect of IRAK1 KD on tumor growth in vivo." (PMID 38796478, 2024). "We next sought to validate IRAK1 protein expression in tumor tissues." (PMID 38796478, 2024). "Additional studies on tumor-associated macrophages (TAMs) and TAM-derived exosomes revealed that miR-192-5p limits the growth and progression of endometrial cancer (EC) through the inhibition of the IRAK1/NF-κB signaling pathway." (PMID 39451208, 2024). "Additionally, IRAK1 expression is elevated in nearly every tumor type, with the exception of thyroid carcinoma (THCA)." (PMID 38792088, 2024). "Moreover, IRAK1 activation in TAMs is reported to promote a STAT3-dependent tumoricidal to tumor-promoting shift towards the M2 polarization of macrophages." (PMID 39451208, 2024). "In addition to promoting a pro-tumorigenic microenvironment, IRAK-1 participates in the crosstalk between cancer cells and CAFs in the tumor microenvironment." (PMID 39451208, 2024). "Moreover, pUL48, a tegument protein of HCMV, can encode DUB for the deubiquitination of TRAF6, TRAF3, IRAK1, IRF7 and STING, thereby inhibiting type I IFN responses, obtaining tumor precursor function, and promoting tumor formation." (PMID 37600809, 2023). "Therefore, IRAK1 acts as an effector of IR-induced anti-tumor immunity on one hand, and meanwhile as a driver of intrinsic tumor radioresistance." (PMID 37031183, 2023). "In this frame, our data indicate that PTX3 secreted by tumor cells promotes the activation of the TLR4/IRAK1 pathway in TNBC cells, and that the expression of PTX3 itself may determine the antitumor responses to TLR4 inhibition." (PMID 37749607, 2023). "The tumor volume and weight of the sh-IRAK1 group were significantly lower than those in the control group, especially following IR treatment, suggesting that the tumors in the IRAK1 depletion group exhibited much more radiosensitivity." (PMID 37031183, 2023). "The resulting Sp1-HDAC1 complex deacetylates H3K56 (histone H3 lysine 56), silences FAS and MIR146A genes and upregulates miR-146a targets such as interleukin-1 receptor-associated kinase 1 (IRAK1) and the chemokine receptor CXCR4, and ultimately promotes tumor invasion, proliferation, and survival." (PMID 37174034, 2023). "MDS patients with high expression of IRAK1 show poor survival and tumor progression." (PMID 37370720, 2023). "However, interleukin-1 receptor associated kinase 1 (IRAK1), a central effector of TLR signaling, has been shown to be responsible for resistance to radiation-induced tumor cell death." (PMID 36226067, 2022). "Notably, a recent report has illuminated the additional conserved role of IRAK1 in the cell survival response to infrared rays and pointed out that IRAK1 contributed to intrinsic tumor resistance to radiotherapy." (PMID 35193602, 2022). "In addition, knockdown of IRAK1 in MDA-MB-231 tumour cells has been shown to reduce primary tumour growth in mouse mammary fat pads and subsequent lung metastasis in NOD/SCID mice." (PMID 36230739, 2022). "IRAK1 is known to be upregulated in human cancers in relation to tumor progression." (PMID 35193602, 2022). "The combination treatment of ginsenoside panaxatriol (GPT) and PTX could inhibit the tumor cells growth and induce apoptosis of TNBC cells resistant to PTX by suppressing interleukin-1 receptor-associated kinase 1 (IRAK1)-mediated NF-κB and ERK pathways." (PMID 35414025, 2022). "The largest difference in IRAK1 levels was observed between normal and tumor tissues." (PMID 36138026, 2022). "Moreover, the inhibition of IRAK1 reduces the resistance of tumor cells against radiotherapy and chemotherapy." (PMID 36421353, 2022). "Altogether, these results suggested that IRAK1 significantly influenced the tumor microenvironment and might be a potential target for PD-1 antibody immunotherapy." (PMID 35669566, 2022).
tumor (continued). "At the pathway level, while several genes involved in TLR signaling (TLR3, TLR4, IRAK1) co-varied positively with Methylibium and Enhydrobacter in healthy control networks, these associations were not identified in tumor networks." (PMID 33863341, 2021). "Thus IRAK1 appears to be able to modulate the host cell immune environment to permit tumor progression." (PMID 34906138, 2021). "Notably, other group recently reported that the expression of IRAK1 was positively correlated with tumor size following neoadjuvant chemotherapy (NCT)." (PMID 32547883, 2020). "Knockdown of AKR1B10 negated IRAK1-induced tumor-initiating cells functions." (PMID 31598161, 2019). "Thus far, the case for IR-induced IRAK1 signaling acting as a driver of intrinsic tumor R-RT is four-fold." (PMID 31799178, 2019). "IRAK1 shRNA inhibition also impaired tumor growth and metastasis in TNBC xenograft models." (PMID 30279971, 2018). "Several lines of evidence implicate IRAK1 in BC tumor growth and metastasis." (PMID 30279971, 2018). "Moreover, subcutaneous xenograft tumor models predict the efficacy of targeting IRAK1 against HCC in vivo." (PMID 27619757, 2016). "Moreover, based on SMMU-7721 HCC xenograft model, IRAK1/4 inhibitor treatment was also used to investigate the pro-tumor effects of IRAK1 in vivo." (PMID 27619757, 2016). "Therefore, a combinatorial approach, targeting IRAK4 and IRAK1, would be a promising endeavor to reduce tumor progression in patients." (PMID 27845762, 2016). "Thus, we propose a model wherein IRAK1 stimulates tumor signaling and phenotypes both independently and in conjunction with DEK." (PMID 26527316, 2015). "To investigate whether IRAK1 is required for metastatic progression in vivo, we first assessed the effects of IRAK1 knockdown on TNBC xenograft mammary fat tumour growth and subsequent lung metastasis progression in NOD/SCID mice." (PMID 26503059, 2015). "Previously, IRAK1 was proposed to have a tumor suppressive role in HNSCCs." (PMID 26527316, 2015). "Although this study focused on the role of IRAK1-driven cytokine network in a cancer cell autonomous manner, IL-1β-mediated IRAK1 activation via tumour-infiltrating immune cell–tumour cell interaction may further enhance oncogenic activity of IRAK1 in vivo." (PMID 26503059, 2015). "For example, miR-146a attenuates pro-inflammatory signaling by directly targeting IRAK1 and TRAF6, key adapters in TLR/NF-κB pathways—mechanistically linked to reduced secretion of IL-6 and TNF-α in epithelial and myeloid systems, a paradigm broadly applicable to tumor contexts." (PMID 41226828, 2025). "Also, IRAK1 could augment the self-renewal, tumorigenicity, and chemoresistance of tumor-initiating cells in HCC." (PMID 35211171, 2022). "Moreover, the inhibition of IRAK1 makes tumor cells sensitive to radiotherapy and chemotherapy." (PMID 36421353, 2022). "Therefore, prospective studies on targeting IRAK1 to anti-tumor immunotherapy are vital." (PMID 35669566, 2022). "Thus, inhibiting the expression level of IRAK1 in the tumor microenvironment may improve anti-tumor immune responses." (PMID 35669566, 2022). "Moreover, IRAK1 was highly expressed in all tumor grades in comparison with normal (p < 0.001)." (PMID 36421353, 2022). "The “one-two punch” hypothesis that IRAK1i will both intrinsically sensitize tumor cells to RT while also allowing for RT-induced antitumor immunity to proceed is further contingent on the use of IRAK1i that are highly specific to IRAK1." (PMID 31799178, 2019). "The inflammasome/IL-1β pathway in the tumor microenvironment may be involved in IRAK1 effects." (PMID 30279971, 2018). "Finally, IRAK-1 activation may also be important for cross talk between cancer cells and other cell populations present in the tumor microenvironment." (PMID 25452754, 2014). "Specifically, miR‐146a‐5p has been reported to bind directly to WNT2, EGFR, NOTCH2, TRAF6, IRAK1 and EIF5A2 to inhibit EMT and act as a tumour suppressor in various human cancers." (PMID 40785027, 2025).